PTH (parathyroid hormone)
Diseases named in the same sentence as PTH in open-access papers (continued):
Sharing a sentence is not in itself a finding about the gene and the disease.
Hypocalcemia (continued). "Multivariate analysis showed that only postoperative PTH was an independent predictor of symptomatic hypocalcemia (OR = 8.05, 95%CI = 3.99-16.22; P = 0.000)." (PMID 29100453, 2017). "Mutant Dsk7/+ and Dsk7/Dsk7 mice were shown to have hypocalcemia and reduced plasma PTH concentrations, similar to ADH2 patients." (PMID 28194447, 2017). "The ROC curves for postoperative PTH were created for both groups to assess the accuracy of PTH as a predictor for the development of post-TT hypocalcemia." (PMID 29100453, 2017). "The workup for hypocalcemia should include measurement of ionized calcium, serum magnesium, intact PTH (iPTH) and vitamin D." (PMID 28730291, 2017). "In particular, ADH1 patients and knock-in mice harboring ADH1-causing Casr mutations have been demonstrated to have a relative or absolute hypercalciuria and high bone mass, in addition to hypocalcemia and low circulating PTH concentrations." (PMID 28194447, 2017). "Subtotal nephrectomized rats presented higher serum concentrations of creatinine, urea nitrogen, and parathyroid hormone, and developed hypocalcemia." (PMID 28439468, 2017). "They suggest that the secondary hyperparathyroidism caused by vitamin D deficiency results in the ability of the parathyroid gland to secrete more PTH and thus protect against the development of postoperative hypocalcemia." (PMID 28955671, 2017). "The current study aimed at evaluating the comparative predictive role of serum calcium and intact parathyroid hormone (iPTH) for post-thyroidectomy hypocalcemia." (PMID 28955671, 2017). "Although the common biochemical features of PTH resistance are hypocalcemia, hyperphosphatemia, and elevated PTH levels, and found in PHP-Ia, PHP-Ic, and PHP-Ib; AHO is the part of clinical picture in PHP-Ia, PHP-Ic, pPHP and occasionally in PHP-Ib." (PMID 29280743, 2017). "Hypocalcemia can arise from insufficiencies of parathyroid hormone (PTH) and/or activated vitamin D. Because hypomagnesemia is known to be one cause of such pathophysiology, it is important to measure serum magnesium level in cases of prolonged hypocalcemia." (PMID 28953654, 2017). "The P221L, K47N and finally E481K mutations are associated with normal serum magnesium levels, and an increased PTH in response to the hypocalcemia." (PMID 28122587, 2017). "Relative parathyroid insufficiency seems to be the principal mechanism of postthyroidectomy hypocalcemia, even in patients with normal postoperative PTH concentrations." (PMID 28545530, 2017). "At the age of 4 years, the patient continued to exhibit persistent hypocalcemia alongside inappropriately low PTH levels." (PMID 28444561, 2017). "Hypocalcemia, hypophosphatemia and increased PTH lead to activation of 1-alpha hydroxylase and inhibition of 24-hydroxylase." (PMID 29280738, 2017). "It has also been proposed that parathyroidectomy can be considered not only for correction of hypocalcemia but also for PTH suppression to maintain metabolic and radiological improvement in HVDRR." (PMID 27796266, 2017). "The results showed the accuracy of postoperative PTH as a predictor for hypocalcemia appeared similar between patients with 25OHD < 20 and≥ 20 ng/mL." (PMID 29100453, 2017). "The secondary hypocalcemia often observed is probably caused by inhibition of the parathyroid gland by the hypomagnesemia, resulting in low levels of parathyroid hormone and eventually leading to hypocalcemia." (PMID 27234911, 2017). "Hypocalcemia and hypophosphatemia with a remarkably increased serum level of Vit D3 and intact parathyroid hormone and alkaline phosphatase levels confirmed the diagnosis of HVDRR." (PMID 29127362, 2017). "Only one patient had persistent symptoms of hypocalcemia with below normal PTH levels at six months after operation." (PMID 29100453, 2017). "Pseudohypoparathyroidism (PHP) is defined as an end-organ resistance to parathormone (PTH) and is characterized by hypocalcemia, hyperphosphatemia, and increased PTH levels." (PMID 27425121, 2017).
Hypocalcemia (continued). "Multiple logistic regression analysis showed that only postoperative PTH was an independent predictor of symptomatic hypocalcemia (OR = 8.05, 95%CI = 3.99-16.22; P = 0.000)." (PMID 29100453, 2017). "Biochemical results showed that most patients were anemic with high C-reactive protein levels, hypocalcemia, hyperphosphatemia, elevated parathyroid hormone and decreased 25-hydroxy vitamin D. At the end of one year, 60 patients died (14.1%)." (PMID 28045952, 2017). "In turn, the synthesis and secretion of PTH is finely regulated by the serum calcium concentration, with hypocalcaemia resulting in a marked increase in the PTH transcripts." (PMID 27655295, 2017). "Early postoperative serum parathyroid hormone (PTH) level has been considered to be an accurate marker for predicting the development of postoperative hypocalcemia." (PMID 29100453, 2017). "Insufficient intake of magnesium reduces the secretion of parathyroid hormone and vitamin D, and leads to hypocalcaemia as well as the disturbance of calcium homeostasis." (PMID 28222767, 2017). "The renal synthesis of 1,25(OH)2D is stimulated by PTH and suppressed by calcium, phosphate and 1,25(OH)2D itself with renal 1α-hydroxylase being stimulated by PTH, hypophosphatemia or hypocalcaemia." (PMID 29280738, 2017). "On the other hand, magnesium depleted patients who present with hypocalcemia despite high iPTH levels suggest bone and kidney resistance to parathyroid hormone." (PMID 27190662, 2016). "PTH secretion occurs in response to hypocalcemia and hyperphosphatemia and is inhibited by severe hypomagnesemia." (PMID 27335606, 2016). "In the postoperative course clinical symptoms of hypocalcemia significantly improved whereas serum calcium and parathyroid hormone (PTH) levels progressively increased into the normal range." (PMID 27488573, 2016). "We report the case of a patient presenting with hypocalcemia and hypokalemia and inappropriately normal parathyroid hormone levels complicating severe magnesium depletion." (PMID 27190662, 2016). "PTH abnormality was reported in one patient manifesting as secondary hyperparathyroidism due to mild hypocalcemia, which was appropriately monitored and managed." (PMID 27413525, 2016). "Autosomal dominant hypocalcemia (ADH) is characterized by hypocalcemia, inappropriately low serum parathyroid hormone concentrations and hypercalciuria." (PMID 26818911, 2016). "Patients with hypocalcaemia due to magnesium depletion also exhibit both renal and skeletal resistance to exogenously administered PTH, as manifested by subnormal urinary cyclic AMP and phosphate excretion and a diminished calcaemic response." (PMID 29546166, 2016). "Results were remarkable for hypocalcemia, hyperphosphatemia, high levels of PTH, normal thyroid function and cerebral calcifications." (PMID 27415614, 2016). "The parathyroid gland elaborates a peptide hormone, parathyroid hormone (PTH) whose primary role is to prevent and/or reverse acute hypocalcemia." (PMID 28018229, 2016). "Mild asymptomatic hypomagnesemia is also known to occur with malaria and this in turn alters the set point of parathyroid hormone release with hypocalcemia." (PMID 27242936, 2016). "Hypoparathyroidism manifests as hypocalcemia and hyperphosphatemia with a low serum parathyroid hormone (PTH) level." (PMID 27957353, 2016). "Biochemical hallmarks of AHD1 are hypocalcemia, which is typically mild to moderate, hyperphosphatemia, hypercalciuria, and inappropriately low but detectable PTH levels." (PMID 27803672, 2016). "The preceding treatment allowed for an appropriate rise in her PTH levels, which then allowed for the correction of the hypokalemia and hypocalcemia that had been refractory to oral replacements." (PMID 27190662, 2016). "In one, autosomal dominant hypocalcemia, there is hypocalcemia and inappropriately normal or frankly low serum PTH levels arising from a reduction in the set-point for extracellular Ca2+." (PMID 28018229, 2016).
Hypocalcemia (continued). "Repeat testing showed persistent hypocalcemia and hyperphosphatemia and low PTH level (<3 pg/mL, reference range 12–72 pg/mL)." (PMID 27957353, 2016). "Despite being the primary biochemical abnormality in PHP type 1A, hypocalcemia with its various clinical expressions (muscle weakness, seizures, etc.)occurs secondary to the rise in PTH." (PMID 27467896, 2016). "Hypocalcemia seems to be related to a reduction of PTH values, which in turn, decreases the release of calcium from bone." (PMID 27588942, 2016). "Parathyroid hormone (PTH) defends the extracellular fluid from hypocalcemia and has powerful and well-documented actions on the skeleton and renal tubular system." (PMID 28018229, 2016). "The patient that underwent reoperation and one patient that got removed one adenoma and two histologically normal glands had relative hypoparathyroidism with mild hypocalcaemia and PTH in the normal range after the last surgery." (PMID 25773486, 2016). "SHPT is caused by reduced phosphate excretion that leads to an increase of fibroblast growth factor-23, a reduced synthesis of 1,25-dihydroxy vitamin D and hypocalcemia, all of which promote parathyroid hormone (PTH) synthesis and release." (PMID 27588942, 2016). "The main reason for hypocalcemia cited in the literature is a blunted response of parathyroid hormone to hypocalcemia, also called “sick euparathyroid state”." (PMID 27242936, 2016). "Impaired parathyroid hormone (PTH) secretion appears to be a major factor in hypomagnesaemia-induced hypocalcaemia." (PMID 29546166, 2016). "The initial laboratory profile of the proband showed severe hypocalcemia, hyperphosphatemia and normal levels of PTH, which was considered to be compatible with primary hypoparathyroidism." (PMID 27415614, 2016). "Only one patient underwent reoperation and had relative hypoparathyroidism with mild hypocalcaemia and PTH within the normal range after the second surgery." (PMID 25773486, 2016). "have established that a decrease of more than 85% in intra-operative PTH is the only predictive and reliable factor in predicting serious postoperative hypocalcemia." (PMID 27737322, 2016). "Initially, the proband's laboratorial presentation with severe hypocalcemia, hyperphosphatemia and normal levels of PTH was compatible with the diagnosis of primary HP." (PMID 27415614, 2016). "Laboratory tests confirmed similar results of hypocalcemia, hyperphosphatemia and high levels of PTH." (PMID 27415614, 2016). "There are factors or conditions that stimulate calcitriol synthesis such as parathyroid hormone (PTH), hypocalcemia and hypophosphatemia, all of which up-regulate CYP27B1." (PMID 26102214, 2015). "Although the mechanism responsible for development of hypocalcemia is unclear, several explanations such as end-organ unresponsiveness to parathyroid hormone (PTH), altered release of PTH, and impaired formation of 1,25-dihydroxy vitamin D3 are offered." (PMID 25542231, 2015). "Another study also demonstrated that changes in combined intact PTH and calcium levels 1 to 6 hours after thyroidectomy were accurate in predicting postoperative hypocalcemia." (PMID 25691901, 2015). "He had concomitant hypocalcaemia (corrected Ca 2.01 mmol/L; normal range 2.10–2.60 mmol/L) but his parathyroid hormone (PTH) level was paradoxically normal (3.9 pmol/L; normal range 1.5–7.1 pmol/L)." (PMID 25138239, 2015). "In order to clarify the mechanism of hypocalcaemia and hypophosphatemia in these patients, we examined the impact of PTH of the osteoblastic cell line MC3T3-E1." (PMID 25775025, 2015). "Hypoparathyroidism in patients with HDR syndrome displays the widest individual variability, ranging from asymptomatic hypocalcemia to paresthesias, muscular aching and a frank tetanic picture, with low, normal or even slightly elevated serum PTH levels." (PMID 26316437, 2015).
Hypocalcemia (continued). "While none of the patients in our series had hypoparathyroidism, two patients had inappropriately low PTH levels in relation to their hypocalcaemia, suggesting possible functional hypoparathyroidism." (PMID 25138239, 2015). "Pseudohypoparathyroidism (PHP) is a group of rare endocrine diseases characterized by hypocalcemia, hyperphosphatemia and an elevation of PTH values due to a variable resistance to this hormone in its target organs, mainly the proximal renal tubule." (PMID 25710380, 2015). "Its biochemical abnormalities include hypocalcemia, hyperphosphatemia and low levels of intact parathyroid hormone (PTH)." (PMID 26649030, 2015). "Summary of five cohort studies evaluating the accuracy of a >65% change in PTH (measured pre‐operation to 1–2 h post‐thyroidectomy) for identifying hypocalcaemia." (PMID 25800943, 2015). "Pseudohypoparathyroidism (PHP) is characterized by hypocalcaemia and hyperphosphataemia due to parathyroid hormone (PTH) resistance." (PMID 25219572, 2015). "Nuf mice were originally identified for having opaque flecks in the nucleus of the lens and have an ADH phenotype characterized by hypocalcemia, hyperphosphatemia, inappropriately reduced plasma PTH concentrations, and ectopic calcification." (PMID 26052899, 2015). "Blood examination showed severe hypocalcemia (5.2 mg/dL) and hyperphosphatemia (4.7 mg/dL) with a relatively low level of intact PTH (7 pg/mL)." (PMID 26514990, 2015). "Hypomagnesaemia is known to induce hypocalcaemia, due to interference with Ca sensing receptor transduction, inhibition of PTH release, end-organ resistance to PTH, and increased breakdown of PTH into inactive metabolites." (PMID 25138239, 2015). "Summary of five cohort studies evaluating the accuracy of a >65% change in PTH (measured pre‐operation to 0–20 min post‐thyroidectomy) for identifying hypocalcaemia." (PMID 25800943, 2015). "Hypomagnesemia was mostly accompanied by hypocalcemia and normal or low parathyroid hormone levels, confirming the existence of a state of secondary hypoparathyroidism in the most severely hypomagnesemic patients." (PMID 26064102, 2015). "One month later, hypocalcemia, hyperphosphatemia and PTH high values persisted (Ca, 6.1mg/dl; P, 7.8mg/dl; PTH, 884pg/dl), the patient being diagnosed of pseudohypoparathyroidism." (PMID 25710380, 2015). "Recent studies have validated the role of postoperative intact PTH measurement in combination with serum calcium levels in predicting postthyroidectomy hypocalcemia and preventing its symptoms." (PMID 25691901, 2015). "A number of adult horses with hypocalcemia have parathyroid gland dysfunction, which is characterized by abnormally low concentrations of parathyroid hormone (PTH)." (PMID 26046642, 2015). "Typical laboratory findings include hypocalcemia, elevated serum PTH, and low-normal, low or undetectable serum 1, 25(OH)2D despite normal or increased serum 25OHD." (PMID 26132292, 2015). "PTH is secreted in response to hypocalcemia after being sensed by the parathyroid calcium-sensing receptor (CaSR)." (PMID 26640724, 2015). "In a study in which rats fed a low-calcium and low-vitamin D diet, severe hypocalcemia resulted in the decline of FGF-23 levels although serum PTH values were elevated." (PMID 26186634, 2015). "Blood tests also indicated severe hypocalcemia [4.2 mg/dl (1.05 mmol/l), corrected calcium 4.7 mg/dl (1.2 mmol/l)], albumin 34.1 g/l (range, 35–50 g/l) and normal PTH values (41 ng/l; range, 15–60 ng/l)." (PMID 26622568, 2015). "Female patients also showed symptoms of hypocalcemia more frequently than male patients, when we compared the same serum calcium and intact PTH subgroups." (PMID 25691901, 2015). "Clinical examination revealed hypocalcemia, hypomagnesemia, nephrocalcinosis, mild myopia, high serum levels of uric acid and intact parathyroid hormone, and moderate chronic kidney disease (stage 3)." (PMID 26136118, 2015).
Hypocalcemia (continued). "Hypoparathyroidism patients were identified through a diagnosis of hypoparathyroidism documented by low PTH levels and hypocalcaemia or normal serum creatinine and hyperphosphataemia in addition to those markers (exact biomarker levels not reported)." (PMID 26010883, 2015). "Teriparatide, a recombinant human PTH, is a potential treatment option in adult transplant recipients with low PTH and refractory hypocalcemia." (PMID 24605319, 2014). "Many authors have demonstrated the correlation between post-thyroidectomy PTH levels and the development of hypocalcemia." (PMID 24476535, 2014). "The typical laboratory findings of primary hypoparathyroidism include hypocalcemia and hyperphosphatemia in the presence of undetectable or abnormally low levels of PTH." (PMID 25280468, 2014). "Increased PTH secretion in response to hypocalcemia is mediated by the calcium-sensing receptor (CaSR) a G-protein coupled receptor (GPCR) located on the parathyroid glands." (PMID 24884838, 2014). "Subsequent unpublished data from 100 consecutive total and completion thyroidectomy patients revealed that approximately half of the patients with 1-hour post-thyroidectomy PTH (1 hr PTH) levels in the range of 9–12 pg/ml will develop hypocalcemia." (PMID 24476535, 2014). "Hypoparathyroidism (HypoPT) is a state of hypocalcemia due to inappropriate low levels of parathyroid hormone (PTH)." (PMID 25101193, 2014). "Almost 100 years ago, Fuller Albright showed that bovine extract of PTH was able to abolish symptomatic hypocalcemia." (PMID 25101193, 2014). "In recent years, multiple retrospective and prospective studies have emerged, which support the use of postoperative serum parathyroid hormone (PTH) levels as accurate predictors of hypocalcemia in postoperative thyroidectomy patients." (PMID 24476535, 2014). "Our unpublished data of 100 subsequent patients between 2003-2007 revealed that approximately half the patients with post-operative PTH levels between 9-12 pg/ml will develop hypocalcemia." (PMID 24476535, 2014). "This syndrome is characterized by persistent hypocalcaemia, hypophosphatemia and hypomagnesaemia due to the fall in PTH levels and occurs in primary and secondary hyperparathyroidism, with the second most frequently." (PMID 24685256, 2014). "There is an open debate in scientific literature regarding the use of early parathyroid hormone (PTH) levels as a predictor of significant hypocalcaemia." (PMID 24684723, 2014). "PTH detection and frozen biopsy were performed during surgery and confirmed the successful excision of the adenoma, while mild hypocalcaemia was noticed postoperatively." (PMID 24685256, 2014). "After discharge, two patients (in total parathyroidectomy group) were readmitted because of postoperative symptomatic recurrent hypocalcemia (PTH:2.39 ng/L and 3.57 ng/L)." (PMID 24886230, 2014). "Different groups have published considerable research on this topic, demonstrating that 1 and 6-hour postoperative PTH and Calcium levels had a high sensitivity and specificity of detecting postoperative hypocalcemia." (PMID 24476535, 2014). "Hypoparathyroidism (HypoPT) is diagnosed on the basis of hypocalcemia with low plasma levels of parathyroid hormone (PTH)." (PMID 25101193, 2014). "In response to reduced serum calcium, a “rebound” in PTH can occur as the body perceives a state of hypocalcemia." (PMID 24884838, 2014). "We found that a that a single postoperative parathyroid hormone (PTH) level, drawn 1 hour after total thyroidectomy, accurately correlated with the development of significant hypocalcemia." (PMID 24476535, 2014). "A single 1-hour post-thyroidectomy PTH level of < 12 pg/ml is a very good predictor of hypocalcemia." (PMID 24476535, 2014). "Whilst the use of serum PTH levels to predict post-thyroidectomy hypocalcaemia is well established, it appears to lack the desirable 100% accuracy rate." (PMID 24267491, 2013).